CHST5 (carbohydrate sulfotransferase 5)
Description:
Sulfotransferase that utilizes 3'-phospho-5'-adenylyl sulfate (PAPS) as sulfonate donor to catalyze the transfer of sulfate to position 6 of non-reducing N-acetylglucosamine (GlcNAc) residues and O-linked sugars of mucin-type acceptors. Acts on the non-reducing terminal GlcNAc of short carbohydrate substrates (in vitro). Preferentially add sulfate onto core 2-based O-glycan structures, but does not act on extended core 1 structures (in vitro). Involved in sulfation of endothelial mucins such as GLYCAM1. Has no activity toward keratan. Not involved in generating HEV-expressed ligands for SELL.
Synonyms: I-GlcNAc6ST; hIGn6ST; GlcNAc6ST-3; Gn6st-3; I-GLCNAC-6-ST; FLJ22167
Tractability: Antibody: UniProt predicts a signal peptide or a membrane-spanning region.
Gene: Protein-coding gene on chromosome 16 (75,528,530 to 75,536,108, reverse strand). Ensembl gene ENSG00000135702.
Subcellular location: Golgi apparatus membrane
Pathways (Reactome):
Metabolism: Keratan sulfate biosynthesis
Gene Ontology:
Molecular function: keratan sulfotransferase activity; N-acetylglucosamine 6-O-sulfotransferase activity; sulfotransferase activity
Biological process: N-acetylglucosamine metabolic process; sulfur compound metabolic process; keratan sulfate proteoglycan biosynthetic process; carbohydrate metabolic process
Cellular component: Golgi apparatus; Golgi membrane; membrane; trans-Golgi network
Genetic constraint (gnomAD): Loss-of-function variants: 1 observed, 2.73 expected, observed/expected ratio (o/e) 0.37, 90% interval 0.13 to 1.55. That is too few expected variants to judge how well the gene tolerates losing a copy. Missense variants: 637 observed, 613.62 expected, observed/expected ratio (o/e) 1.04, 90% interval 0.97 to 1.11. Synonymous variants: 313 observed, 285.69 expected, observed/expected ratio (o/e) 1.1, 90% interval 1 to 1.2.
Homologues: Orthologues: chimpanzee CHST5 (99% identical), Drosophila melanogaster CG31637 (22% identical), Drosophila melanogaster CG9550 (16% identical). Paralogues in human: CHST6 (81% identical), CHST4 (48% identical), CHST2 (35% identical), CHST7 (34% identical), CHST3 (30% identical), CHST1 (30% identical).
Diseases named in the same sentence as CHST5 in open-access papers:
CHST5 is named in the same sentence as 1 disease in open-access papers, as found by Europe PMC text mining. Sharing a sentence is not in itself a finding about the gene and the disease. The quoted sentences say what the papers report.
cancer (2 papers, 2014 to 2022). A tumor composed of atypical neoplastic, often pleomorphic cells that invade other tissues. "The duplication encompasses 6 genes four of which are frequently deregulated in cancer (TMEM170A, CHST6, CHST5, TMEM231)." (PMID 35221838, 2022).